GJB1 (gap junction protein beta 1)
Description:
One gap junction consists of a cluster of closely packed pairs of transmembrane channels, the connexons, through which materials of low MW diffuse from one cell to a neighboring cell.
Synonyms: Cx32; CMTX; CMTX1
Tractability: Small molecule: a structure with a bound ligand is known. Antibody: UniProt places it where antibodies can reach, with medium confidence; UniProt predicts a signal peptide or a membrane-spanning region; its Gene Ontology location is reachable by antibodies, with medium confidence. PROTAC: ubiquitination databases record sites on it; its protein half-life has been measured.
Gene: Protein-coding gene on chromosome X (71,212,811 to 71,225,519, forward strand). Ensembl gene ENSG00000169562.
Subcellular location: Cell membrane; Cell junction, gap junction
Pathways (Reactome):
Vesicle-mediated transport: Gap junction assembly; Oligomerization of connexins into connexons; Transport of connexins along the secretory pathway
Developmental Biology: EGR2 and SOX10-mediated initiation of Schwann cell myelination
Gene Ontology:
Molecular function: protein binding; gap junction channel activity; identical protein binding
Biological process: cell-cell signaling; gap junction assembly; nervous system development; cell communication; transmembrane transport
Cellular component: connexin complex; endoplasmic reticulum membrane; cytoplasm; gap junction; plasma membrane
Gene-disease validity (ClinGen):
ClinGen rates the evidence that GJB1 causes each of these diseases.
Charcot-Marie-Tooth disease X-linked dominant 1 (X-linked): Definitive. Charcot-Marie-Tooth neuropathy that is inherited in an X-linked manner, and is associated with mutation(s) in the GJB1 gene, encoding gap junction beta-1 protein.
Homologues: Orthologues: chimpanzee GJB1 (100% identical), macaque GJB1 (100% identical), dog GJB1 (99% identical), mouse Gjb1 (99% identical), rat Gjb1 (99% identical), rabbit GJB1 (98% identical), pig GJB1 (98% identical), tropical clawed frog gjb1 (69% identical), zebrafish gjb1b (64% identical), zebrafish gjb1a (56% identical). Paralogues in human: GJB2 (51% identical), GJB6 (51% identical), GJB4 (43% identical), GJB3 (41% identical), GJA3 (41% identical), GJB5 (41% identical), GJA8 (40% identical), GJA1 (39% identical), GJA9 (39% identical), GJA4 (38% identical), GJA5 (37% identical), GJB7 (37% identical), and 8 more.
Diseases named in the same sentence as GJB1 in open-access papers:
GJB1 is named in the same sentence as 141 diseases in open-access papers, as found by Europe PMC text mining. Sharing a sentence is not in itself a finding about the gene and the disease. The quoted sentences say what the papers report.
Charcot-Marie-Tooth disease (23 papers, 2009 to 2025). An inherited degenerative disorder involving the peripheral nerves. "Cx32 plays such a critical role in the function of the Schwan cell that mutations in GJB1 (the gene that codes for Cx32) lead to Charcot-Marie-Tooth disease." (PMID 36140338, 2022). "To date, over 30 cases of white matter lesion involvement in patients with Charcot-Marie-Tooth disease and 22 GJB1 gene mutations have been described." (PMID 31842800, 2019). "We recently created and analyzed transgenic mouse lines that expressed a human mutated GJB1 (i.e., the gene involved in the X-linked form of Charcot-Marie-Tooth disease), coding for connexin 32 (Cx32), a component of gap junctions." (PMID 25947624, 2015). "The critical role of GJCs in the functioning of myelinating SCs is evident in Charcot-Marie-Tooth disease (CMT), X-linked form 1 (CMTX1), which is caused by mutations in the gap junction protein beta 1 (GJB1) gene that codes for Cx32." (PMID 30881289, 2019).
neuropathy (23 papers, 2014 to 2026). A disorder affecting the nervous system that manifests with pain, tingling, numbness, and/or muscle weakness. "AAV9 and AAVrh10 vectors expressing either EGFP or the neuropathy-associated gene GJB1/Connexin32 (Cx32) under a myelin specific promoter were injected intrathecally or intravenously in wild type and Gjb1-null mice, respectively." (PMID 34857831, 2021). "In order to achieve Schwann cell-specific expression, we used the PNS myelin-specific Mpz promoter and delivered AAV vectors carrying either the reporter gene Egfp or the neuropathy associated gene GJB1 by lumbar intrathecal or by intravenous injection." (PMID 34857831, 2021). "In other studies we also found that similar expression rates and lower than physiological expression levels of the neuropathy-associated gene such as GJB1 (connexin 32) were still adequate to provide a significant therapeutic benefit in disease models, although not a complete rescue." (PMID 30907403, 2019). "Advances in molecular genetics have identified key causative genes, including PMP22, MPZ, MFN2, TTR, EGR2, and CX32 (GJB1), which are implicated in Charcot–Marie–Tooth disease, Dejerine–Sottas syndrome, and related neuropathies." (PMID 41595476, 2026). "The X-linked CMT1X neuropathy represents the second most common CMT form and is the consequence of mutations in the GJB1 gene, which encodes the CX32 (connexin 32) protein." (PMID 38678519, 2024). "In Gjb1-null mice, significant elevation of Ncam1 is evident from 6 months, after the onset of the neuropathy which occurs at 3 months of age." (PMID 35148379, 2022). "Recommendation 28: If an X-chromosomal CMT neuropathy is suspected, we recommend analysis of the GJB1 gene including coding regions, untranslated regions (UTRs), and promoter regions." (PMID 34438578, 2021). "Regarding the genetical bases of the inherited neuropathies, the three most common forms have been identified as resulting from mutations in the Schwann cell‐related myelin genes for PMP22, Cx32 (GJB1), and P0 (MPZ)." (PMID 26250643, 2016). "It is well established that Cx32/GJB1‐null mice (CMT1X model) exhibit CMT‐like neuropathy with slowed conduction and progressive myelin defects, whereas MAG‐null mice display related myelin and functional abnormalities and have been suggested to mimic aspects of HNPP." (PMID 41400104, 2026). "Gap Junction Protein Beta-1 (encoded by GJB1), also known as connexin 32 (Cx32), is located on the X-chromosome accounting for X-linked Charcot-Marie-Tooth (CMTX), which represent at least 10% of CMT neuropathies." (PMID 33542455, 2022). "Furthermore, we have previously shown that both serum Ncam1 levels and clinical symptoms of the neuropathy are restored to wild-type levels following targeted gene therapy in the Gjb1-null mice." (PMID 35148379, 2022). "According to larger studies following comparable protocols, we can genetically identify the four most frequent genes (PMP22, GJB1/Cx32, MPZ/P0, MFN2) in 40–60% of patients in whom an inherited neuropathy is suspected." (PMID 34438578, 2021). "However, it still accounts for 7.5% of molecularly unassigned demyelinating CMT in the absence of PMP22 duplication, GJB1 mutations or MPZ mutations, as well as 1.9% of HNPP-like neuropathy of unknown genetic causes in Taiwan." (PMID 29127354, 2017).
breast carcinoma (14 papers, 2013 to 2024). "We disclosed the expression of five connexin isotypes by confirming the production of GJA1/Cx43, GJA3/Cx46 and GJB2/Cx26 and detecting, for the first time, GJA6/Cx30 and GJB1/Cx32 both in the human pre-menopausal mammary gland and breast carcinomas." (PMID 25383624, 2014). "The expression of GJA1/Cx43, GJA3/Cx46 and GJB2/Cx26 and, for the first time, GJA6/Cx30 and GJB1/Cx32 was revealed both in normal human mammary glands and breast carcinomas." (PMID 25383624, 2014). "Based on mRNA expression data, a comprehensive screening for five connexin isotypes, GJA1/Cx43, GJA3/Cx46, GJB2/Cx26, GJA6/Cx30 and GJB1/Cx32 was performed at the protein level in normal pre-menopausal breast glands and in a cohort of cancers representing all grades and major breast cancer subtypes." (PMID 25383624, 2014).
X-linked Charcot-Marie-Tooth disease (11 papers, 2015 to 2024). "GJB1 (Cx32) gene mutations cause the X-linked Charcot-Marie-Tooth disease, a disease of the peripheral nervous system, where Schwann cells fail to provide metabolic or trophic support for the physiological function of axons." (PMID 33117125, 2020). "X-linked Charcot-Marie-Tooth disease (CMTX) is a hereditary neuropathy caused by mutations in GJB1 coding for connexin-32 (Cx32), a gap-junction protein expressed in peripheral Schwann cells and oligodendrocytes within the central nervous system (CNS)." (PMID 25883816, 2015). "Finally, the inherited peripheral neuropathy X-linked Charcot-Marie-Tooth disease can be caused by mutations in GJB1, which encodes Cx32." (PMID 32332093, 2020). "X-linked Charcot-Marie-Tooth disease (CMTX) is a hereditary neuropathy resulting from a mutation in the GJB1 (Gap Junction protein beta 1) gene responsible for the expression of Cx32 in Schwann cells and oligodendrocytes." (PMID 36140338, 2022).
prostate carcinoma (9 papers, 2013 to 2024). A carcinoma that arises from epithelial cells of the prostate gland. "High expression of GJB1 in prostate cancer inhibits prostate cancer invasion and metastasis and is considered the most predictive prostate cancer marker in urine." (PMID 38818039, 2024). "In addition, the three target genes (DTNA, GJB1, and TRPC4) we searched for are also expected to be used for prostate cancer diagnosis and treatment in the future." (PMID 38818039, 2024).
deafness (6 papers, 2008 to 2022). An inherited or acquired condition characterized by the complete loss of the ability to hear from one or both ears. "Furthermore, GJC3 (encoding Cx30.2/31.3), GJB3 (encoding Cx31), GJB1 (encoding Cx32), and GJA1 (encoding Cx43) gene mutations have been reported to cause non-syndromic deafness." (PMID 35457072, 2022).
lung carcinoma (6 papers, 2014 to 2025). "GJB1 enhanced the metastasis and invasion of lung cancer cells." (PMID 40575171, 2025).
and sensory neuropathy (5 papers, 2016 to 2021). "Charcot-Marie-Tooth type X1 (CMTX1), the second most common hereditary motor and sensory peripheral neuropathy, is caused by mutations in the gap junction beta 1 (GJB1) gene." (PMID 34089394, 2021). "CMT1X is the second most common form of hereditary motor and sensory neuropathy and is caused by more than 400 different mutations in the GJB1 gene that encodes Cx32." (PMID 31232168, 2019). "Mutations in the GJB1 gene, which encodes Cx32, are the leading cause of the X-linked dominant form of Charcot–Marie–Tooth disease (CMT1X or CMTX1), the second most common form of hereditary motor and sensory neuropathy and a disease for which there is no cure." (PMID 30042657, 2018). "A large deletion of the GJB1 gene was found by our CNV analysis in one patient with progressive peripheral motor and sensory neuropathy." (PMID 27549087, 2016).
epilepsy (5 papers, 2014 to 2025). A brain disorder characterized by episodes of abnormally increased neuronal discharge resulting in transient episodes of sensory or motor neurological dysfunction, or psychic dysfunction. "Gjb1 encodes connexin-32, whose expression increases across postnatal cortical development to form gap junctions in oligodendrocytes and neurons and is implicated in epilepsy." (PMID 36831303, 2023). "Increased transcription of GJB1 mRNA has also been observed in a 4-aminopyridine-induced epilepsy model in Wistar rats." (PMID 40217413, 2025). "In addition, we observed some downregulated genes (such as MPZ, GJB1, CDH15, KCNQ3, and PLP1) in K-NSC cells, and abnormal expression of these genes has been reported to cause cognitive impairment, epilepsy, spasticity, and myelin abnormalities, which are similar to the disease symptoms of GLD." (PMID 37076788, 2023).
leukodystrophy (5 papers, 2019 to 2025). Leukodystrophies are a group of rare, progressive, metabolic, genetic diseases that affect the brain, spinal cord and often the peripheral nerves. "In addition, several hereditary disorders can present with CCPD and may overlap with acute immune-mediated demyelinating processes, including Charcot–Marie–Tooth disease (particularly GJB1-related/CMTX1), mitochondrial disorders, and leukodystrophies." (PMID 41181092, 2025).
melanoma (5 papers, 2011 to 2025). A malignant, usually aggressive tumor composed of atypical, neoplastic melanocytes. "Metastatic melanomas showed the loss of GJA1 (Cx43) protein, the increase in cytoplasmic GJB2 (Cx26), and the upregulation of both GJC3 (Cx30.2) and GJB1 (Cx32) through melanoma progression, compared to melanocytes." (PMID 40227837, 2025). "In silico data revealed downregulation of GJA1/Cx43 and GJB2/Cx26 mRNA, in addition to upregulated GJB1/Cx32, during melanoma progression." (PMID 30717194, 2019). "In three melanoma cell lines, we also showed the loss of GJA1/Cx43 and the differential expression of GJB1/Cx32, GJB2/Cx26, GJA3/Cx46 and GJC3/Cx30.2." (PMID 30717194, 2019). "Though other groups also found Cx32 transcripts in some melanomas, ours is the first, by using three different TaqMan probes and a Western blot-verified antibody, to show unequivocal evidence of both GJB1 transcript and Cx32 protein in melanoma cell lines; and Cx32 protein in melanoma tissues." (PMID 30717194, 2019). "In datasets using GSE3189 arrays, melanomas showed downregulated GJA1 (Cx43; LogFC = −4.1; p < 0.001), GJB3 (Cx31; LogFC = −3.4; p < 0.001), GJB5 (Cx31.1; LogFC = −3.3; p < 0.001) and upregulated GJB1 (Cx32; LogFC = +1.5; p < 0.001) gene expression compared to nevi." (PMID 30717194, 2019). "The microarray results indicated that microenvironmental cues can trigger switching of melanoma cells to a neural stem cell-like pattern, as six genes related to neural stem cell and neural stem cell niche biology were upregulated: SOX2, ID4, GFRA2, S100A4, LGI4, and GJB1." (PMID 25642713, 2015). "Such five genes (namely, SCNN1A, GJB3, KCNK7, GJB1, KCNN2) are novel potential melanoma markers or molecular targets, never previously related to melanoma." (PMID 30934896, 2019). "Five such genes (namely: SCNN1A, GJB3, KCNK7, GJB1, KCNN2) were identified as potential strong melanoma markers that had never been identified before." (PMID 30934896, 2019). "The network between two genes involved in cell connecting interactions (GJB1 and DES) showed a negative and higher correlation (r = -0.943) in stage II melanoma patients when compared to stage III melanoma patients (r = 0.54)." (PMID 22032772, 2011). "GJB1 (Cx32) could not be detected in MC, but it was highly expressed in all three melanoma cell lines: WM983/A (dCt = 6.65; SD = 0.23), HT199 (dCt = 5.25; SD = 0.42) and A2058 (dCt = 4.92; SD = 0.14), though Hs.PT.56a.4848609 TaqMan probe could not detect GJB1 mRNA in HT199 and A2058 cells." (PMID 30717194, 2019).
ovarian carcinoma (5 papers, 2019 to 2024). A malignant neoplasm originating from the surface ovarian epithelium. "Destruction of GJB1 plays a role in promoting the occurrence and development of ovarian cancer and is not conducive to the action of chemical drugs." (PMID 38454924, 2024).
X-linked Charcot-Marie-Tooth disease type 1 (5 papers, 2019 to 2026). "X-linked Charcot-Marie-Tooth disease type 1 (CMTX1) is a rare inherited neuropathy caused by mutations in the GJB1 gene, leading to progressive distal muscle weakness and atrophy." (PMID 41757265, 2026). "X-linked Charcot-Marie-Tooth Disease type 1(CMT1X) is the second most common form of inherited peripheral neuropathy that is caused by mutations in the gap junction beta-1 (GJB1) gene." (PMID 36225735, 2022). "X-linked Charcot-Marie-Tooth disease type 1 (OMIM #302800) is characterized by progressive muscle weakness and atrophy associated with mutations in the GJB1 gene, coding for connexin Cx32 (Cx32)." (PMID 31780897, 2019). "X-linked Charcot-Marie-Tooth disease type 1 (CMTX1), the second most common cause of hereditary neuropathy, is caused by mutations in GJB1, which codes for connexin 32 (Cx32)." (PMID 32010055, 2019). "X-linked Charcot-Marie-Tooth disease type 1 (CMTX1) is a dominantly inherited peripheral neuropathy and is caused by mutations in gap junction beta 1 gene (GJB1)." (PMID 31068899, 2019).
glioblastoma (4 papers, 2018 to 2025). The most malignant astrocytic tumor (WHO grade IV). "GJB1 and GJB2 are highly expressed in glioblastoma and PC, which are closely related to chemotherapy resistance." (PMID 40575171, 2025).
Stroke (4 papers, 2019 to 2021). Sudden impairment of blood flow to a part of the brain due to occlusion or rupture of an artery to the brain. "GJB1 mutations should be a consideration in the differential diagnosis of recurrent reversible stroke-like symptoms in children." (PMID 32010055, 2019). "The case of patient 11 reminds us that GJB1 mutations should be a consideration in the differential diagnosis of recurrent reversible stroke-like CNS deficits in children, even without evidence of peripheral neuropathy." (PMID 32010055, 2019).
oculodentodigital dysplasia (3 papers, 2013 to 2023). Oculodentodigital dysplasia (ODDD) is characterized by craniofacial, neurologic, limb and ocular abnormalities. "Moreover, mutations in the Cx32 gene (GJB1) are involved in the pathogenesis of X-linked Charcot–Marie–Tooth neuropathy, while mutations in the gene encoding Cx43 (GJA1) result in oculodentodigital dysplasia." (PMID 23596415, 2013).
peripheral demyelinating neuropathy (3 papers, 2013 to 2023). "Therefore, many mutations of GJB1, which encodes Cx32, cause X‐linked Charcot–Marie–Tooth disease, an inherited peripheral demyelinating neuropathy in which large CNS white matter lesions occasionally emerge." (PMID 36368713, 2023). "The frequency of PMP22 duplications among the demyelinating polyneuropathy patients in this material was lower than average (18.7%), whereas the frequency of MPZ mutations (6.0%) and GJB1 mutations (6.7%) were close to average." (PMID 24053775, 2013).
Ataxia (2 papers, 2021 to 2023). Ataxia refers to impaired coordination of voluntary muscle movement. "CMT patients with NEFL and GJB1 mutations exhibited diverse cerebellar involvements, including cerebellar ataxia, dysarthria, dyssynergia, and dysmetria." (PMID 34768465, 2021). "We found structural evidence of cerebellar WM abnormalities in CMT patients with NEFL and GJB1 mutations and an association between cerebellar WM involvement and cerebellar ataxia in these genetic subtypes, especially in the NEFL subgroup." (PMID 34768465, 2021). "Nevertheless, MRI volumetry or DTI can be helpful for early detection of cerebellar dysfunction in CMT patients with NEFL and/or GJB1 mutations, especially in cases harboring cerebellar ataxia." (PMID 34768465, 2021). "In particular, the frequency of the cerebellar ataxia was high in patients with NEFL mutations (72.7%), compared to GJB1 mutations (9.1%), PMP22 duplication (0%), and MFN2 mutations (0%)." (PMID 34768465, 2021). "In addition, cerebellar ataxia, which is commonly manifested in patients with NEFL mutations, is not well observed in the other genetic mutations, such as PMP22 and MFN2, except in 1 out of 11 patients with GJB1 mutations." (PMID 34768465, 2021).
carcinoma of the pancreas (2 papers, 2023 to 2025). "High expression of GJB1 and GJB2 was also associated with lymph node metastasis and prognosis in carcinoma of the pancreas." (PMID 40575171, 2025).
Cerebellar atrophy (2 papers, 2021 to 2023). Cerebellar atrophy is defined as a cerebellum with initially normal structures, in a posterior fossa with normal size, which displays enlarged fissures (interfolial spaces) in comparison to the foliae secondary to loss of tissue. "Furthermore, the GJB1 p.P58S variant is responsible for X‐linked spinocerebellar ataxia, which presents with progressive ataxia and cerebellar atrophy with spinocerebellar and corticospinal tract demyelination." (PMID 36368713, 2023). "However, there was no statistically significant cerebellar atrophy in the other genotypes (PMP22 duplication, MFN2, or GJB1 mutation)." (PMID 34768465, 2021).